ATF3 (activating transcription factor 3)
Diseases named in the same sentence as ATF3 in open-access papers (continued):
Sharing a sentence is not in itself a finding about the gene and the disease.
colon carcinoma (continued). "In colon cancer, down-regulating ATF3 in HT29 colon cancer cells with antisense oligonucleotides apparently diminished entopic tumor growth and metastasis in mice." (PMID 21129190, 2010). "In the present study, we sought to clarify ATF3 regulation and its role in human colon cancer using xenogenic mouse models." (PMID 21129190, 2010). "RNAi mediated knock-down of ATF3 in HCT116 colon cancer cells significantly increased cancer cell migration in vitro." (PMID 21129190, 2010). "We conclude from these experiments that ATF3 expression in colon cancer cells is complexly controlled through the interaction of multiple molecular signaling pathways." (PMID 21129190, 2010). "We previously observed that treatment of HCT116 and SW620 colon cancer cells with an Hsp90 inhibitor (17-DMAG) substantially up-regulates constitutive ATF3 expression." (PMID 21129190, 2010). "Our recent observation that Hsp90 inhibition induces ATF3 in cancer cells and the lack of clarity regarding the biological effect of this transcription factor in oncology pressed our aim to define the role of ATF3 in colon cancer." (PMID 21129190, 2010). "Treatment of colon cancer cell lines with 5-FU induced ATF3 along with other DNA damage response genes (GADD34, GADD45α, PCNA)." (PMID 20137089, 2010). "Together, these in vitro experiments indicate that ATF3 down-regulation harbors the potential to increase the metastatic potential of colon cancer cells." (PMID 21129190, 2010). "We conclude that ATF3 is likely to be down-regulated in colon cancers, hence supporting the rationale of therapeutically inducing ATF3 expression in this cancer entity." (PMID 21129190, 2010). "For instance, ATF3 enhances colon cancer metastasis by increasing cell motility and invasion." (PMID 40754247, 2025). "Meanwhile, decreased ATF3 expression could attenuate ionizing radiation (IR)–induced ferroptosis damage in colon cancer cells." (PMID 39171207, 2024). "Additionally, the overexpression of ATF3 decreased the tumor size in human colon cancer xenografts and inhibited cell migration and invasion, suggesting the tumor suppressive effect of ATF3." (PMID 34571936, 2021). "Conversely, knockdown of ATF3 suppressed the motility and invasion of colon cancer cells." (PMID 34571936, 2021). "Similarly, ATF3 was reported to promote cell invasion and to contribute to tumor spreading in colon cancer." (PMID 33050633, 2020). "In spite of a low ATF3 mutation rate (0.1%), a colon cancer was found to harbor an ATF3 mutation (K108delK) lacking K108—a residue required for ubiquitination." (PMID 31796886, 2020). "The effects of ATF3 expression are especially complicated in colon cancer." (PMID 32922364, 2020). "However, several studies indicated that ATF3 expression is upregulated in human colon cancer specimens and promotes tumor growth and migration in HT29 colon cancer cells." (PMID 32922364, 2020). "We found that ATF3 expression was highly induced in all three human colon cancer cell lines." (PMID 33082907, 2020). "However, siRNA-mediated knockdown of ATF3 attenuates motility and invasion of the colon cancer cell." (PMID 32922364, 2020). "For example, increased levels of miR-34a are known to decease cAMP response element-binding protein (CREB) to drive neuronal dysfunction in HIV-induced neurocognitive disorders, and to increase AMP-dependent transcription factor 3 (ATF3) levels in colon cancer." (PMID 33228131, 2020). "Importantly, down-regulation of ATF3 markedly increased the migration ability of colon cancer cells in vitro." (PMID 21129190, 2010). "Human colon cancer tissues were analyzed for ATF3 expression." (PMID 21129190, 2010). "In conclusion, ATF3 down-regulation in colon cancer promotes tumor growth and metastasis." (PMID 21129190, 2010). "In colon cancer, the effects of ATF3 expression are particularly perplexing." (PMID 21129190, 2010).
colon carcinoma (continued). "Here we followed-up on our previous observation that inhibition of Hsp90 may increase ATF3 expression and sought to determine the role of ATF3 in colon cancer." (PMID 21129190, 2010). "Thus, drug-induced overexpression of ATF3 may have beneficial effects in only a subset of colon cancer cells." (PMID 21129190, 2010). "Thus, the present study not only adds an interesting new aspect to the multiple mechanisms of Hsp90-inhibition, but also provides reasonable evidence that an ATF3-induction by Hsp90 inhibition could be favorable for therapy of advanced colon cancer." (PMID 21129190, 2010). "However, we additionally observed on a protein level that inhibition of either MAPK/Erk (UO126), or p38 (SB203580), could also up-regulate ATF3 expression in colon cancer cells." (PMID 21129190, 2010). "In this study, we clearly show that ATF3 is a direct transcriptional target gene of the Wnt/β-catenin pathway in normal human and HCT116 colon cancer cells." (PMID 29966001, 2018). "Towards this end, we constructed an AAV targeting vector containing left (LA) and right homology arms (RA) flanking the exon 3 of the ATF3 gene, and introduced the vector into HCT116 human colon cancer cells via rAAV infections." (PMID 27146783, 2016). "In GANT61-treated human colon carcinoma cells, novel DNA damage-inducible transcripts DDIT3 (GADD153), DDIT4 (REDD1), DDIT2 (GADD45G), PPP1R15A (GADD34) and ATF3 were significantly up-regulated concomitant with the arrest of cells at G1/S." (PMID 20957031, 2010). "Importantly, ATF3 expression was lower in human colon cancer specimens, as compared to corresponding normal surrounding tissues, suggesting that ATF3 may represent a down-regulated tumor suppressor in colon cancer." (PMID 21129190, 2010). "One of these molecules is activating transcription factor-3 (ATF3), which is Hsp90-inhibitor inducible in HCT116, SW620 and HT29 colon cancer cells." (PMID 21129190, 2010). "We conclude from these experiments that ATF3 functions as a tumor suppressor and growth-inhibitory factor in HCT116 colon cancer." (PMID 21129190, 2010). "In conclusion, the present study shows that down-regulation of ATF3 enhances both invasive properties and tumor metastasis of HCT116 colon cancer cells in vivo." (PMID 21129190, 2010). "In one respect, ATF3 was shown to be overexpressed in human colon cancer specimens and appears to promote tumor growth and migration in an experimental HT29 colon cancer model." (PMID 21129190, 2010). "NAR upregulates ATF3 expression in HCT116, SW480, LoVo, and HT-29 colon cancer cells." (PMID 32922364, 2020). "Therefore, though ATF3 is activated downstream of the Wnt/β-catenin pathway, it acts as a negative regulator of the migration and invasion of HCT116 human colon cancer cells exhibiting aberrant Wnt/β-catenin activity." (PMID 29966001, 2018). "Finally, we demonstrated that ATF3 is a direct target gene of β-catenin/TCF4 binding and negatively regulates tumor progression in human colon cancer cells." (PMID 29966001, 2018). "However, two independent studies showed that ATF3 appears to promote tumor growth and migration in the experimental HT29 colon cancer model by either ATF3 antisense oligonucleotide or adenovirus-mediated overexpression of ATF3." (PMID 28402947, 2017). "Moreover, targeting ATF3 for knockdown inhibits cell adhesion and invasion capability in HT29 human colon cancer cells." (PMID 22768301, 2012). "These in vivo experiments support the hypothesis that ATF3 functions as a tumor suppressor and anti-metastatic factor in HCT116 colon cancer." (PMID 21129190, 2010). "Thus, we propose that ATF3 functions as a tumor suppressor and anti-metastatic factor in HCT116 colon cancer." (PMID 21129190, 2010). "Hence, results from this study suggest that ATF3 functions as a tumor suppressor and anti-metastatic factor in HCT116 colon cancer, which is therapeutically inducible by blocking Hsp90." (PMID 21129190, 2010).
colon carcinoma (continued). "In view of the fact that ATF3 is stress-inducible and continuously detectable in colon cancer cells, we used an shRNA approach for specifically targeting ATF3 in HCT116 colon cancer cells, with the intention to determine the biological effects of a further ATF3 down-regulation in this cancer entity." (PMID 21129190, 2010). "In colon cancers, ATF3 plays a role in regulating genes downstream of protein kinase-like endoplasmic reticulum kinase (PERK) and PERK-eIF2α signaling during instances of endoplasmic reticulum stress; on the other hand, ATF3 plays an important role in berberine-induced apoptosis." (PMID 30376856, 2018). "Similarly in a very recent study, ATF3 was identified as one of a number of genes induced following a genetic screen of an HDAC inhibitor in sensitive colon cancer cell lines although the mechanism of induction was not characterized." (PMID 20828393, 2010). "In addition, ATF3 modulates trans-10, cis-12-CLA-stimulated non-steroidal anti-inflammatory drug-activated gene-1 (NAG-1) expression, and apoptosis in colon cancer cells." (PMID 32922364, 2020).
glioma (36 papers, 2014 to 2026). A benign or malignant brain and spinal cord tumor that arises from glial cells (astrocytes, oligodendrocytes, ependymal cells). "A log-rank test comparing high and low ATF3 expression groups within glioma samples revealed that high ATF3 expression was associated with poorer overall survival (Logrank_P = 8.76E-19; hazard ratio = 2.15 (1.81–2.56)." (PMID 40837407, 2025). "Six overlapping genes included ATF3, associated with stemness in glioma stem cells (GSCs)." (PMID 40730548, 2025). "Therefore, in this study, we investigated the roles of ferroptosis and ATF3 in brucine-induced glioma cell death and its underlying mechanism." (PMID 34112960, 2021). "We uncovered a potential oncogenic role for CCDC86 in glioma progression and identified activating transcription factor 3 (ATF3) as a downstream target gene." (PMID 40837407, 2025). "The impact of CCDC86 in glioma was further defined with the identification of ATF3 as a downstream target gene, a transcription factor pivotal in regulating genes involved in cellular stress and cell cycle progression." (PMID 40837407, 2025). "ATF3 was also found to be up-regulated in glioma cells compared with normal human embryonic brain cells." (PMID 40837407, 2025). "In this section, this study aimed to assess the roles of CCDC86 and ATF3 in glioma development in vitro and in vivo." (PMID 40837407, 2025). "ATF3 contributes to brucine-triggered glioma cell ferroptosis via promotion of hydrogen peroxide and iron." (PMID 39193375, 2024). "Brucine, an indole alkaloid extracted from the seeds of Strychnos nux-vomica L. (Loganiaceae), activates endoplasmic reticulum stress in glioma cells, resulting in the upregulation of activating transcription factor 3 (ATF3) and its nuclear translocation." (PMID 38292937, 2024). "Data from GEPIA2 also showed frequently increased FOS, JUNB, JUN, and ATF3 in glioma, especially GBM samples, compared to normal brain tissues." (PMID 39257581, 2024). "So we proceeded to knock down ATF3 and demonstrated by the same phenotypic experiments that ATF3 can promote malignant progression of glioma." (PMID 35871061, 2022). "Previous studies have shown that ATF3 plays an anti-tumor function, and the overexpression of ATF3 reduces the migration and proliferation capacities of metastatic glioma cells." (PMID 36276638, 2022). "ATF3 was reported overexpressed in glioma cohorts, and ATF3-knockdown was able to reduce the proliferative and invasive activity of glioma cell lines U373MG both in vitro and in vivo." (PMID 35871061, 2022). "At the same time, ATF3 has been reported to be involved in brucine-induced ferroptosis of glioma cells." (PMID 36340581, 2022). "Taken together, ATF3 contributes to brucine-induced glioma cell ferroptosis via increasing H2O2 and iron." (PMID 34112960, 2021). "In this study, we showed that brucine inhibited glioma cell growth in vitro and in vivo, which was paralleled by nuclear translocation of ATF3, lipid peroxidation, and increases of iron and H2O2." (PMID 34112960, 2021). "To clarify the factor accounting for brucine-induced glioma cell ferroptosis, we isolated cytoplasmic and nuclear fractions and used Western blotting to analyze brucine-induced changes in ATF3, given that ATF3 plays a crucial role in regulating cell demise." (PMID 34112960, 2021). "In conclusion, we demonstrate in this study that brucine activated ER stress in glioma cells, which results in ATF3 upregulation and nuclear translocation." (PMID 34112960, 2021). "In summary, we found in this study that brucine inhibited glioma cell growth in vitro and in vivo, which was paralleled by nuclear translocation of ATF3, increases of iron and H2O2, and lipid peroxidation." (PMID 34112960, 2021).
glioma (continued). "Accordingly, LDH release assay proved that knockdown of ATF3 significantly prevented brucine-induced glioma cell death." (PMID 34112960, 2021). "In this study, we found brucine induced ATF3 upregulation and translocation into nuclei in glioma cells." (PMID 34112960, 2021). "Then, we introduced siRNA to knock down ATF3 and examined its effect on brucine-induced iron increase, lipid peroxidation, and glioma cell death." (PMID 34112960, 2021). "To further support the notion that ATF3 represses SLC7A11 expression, we analyzed publicly available gene expression datasets and found that the ATF3 expression level inversely correlated with the SLC7A11 level in two cohorts of glioma patients." (PMID 31273299, 2020). "The purpose of this study was to investigate the function of ATF3 in the development of glioma and its clinical significance." (PMID 25872784, 2015). "ATF3 protein expression was detected in both the normal brain tissues and glioma tissues of each grade." (PMID 25872784, 2015). "The relative mRNA expression of ATF3 in the glioma tissues of grade II, III and IV was 3.23±0.51, 5.24±0.43 and 6.37±0.45, respectively, significantly higher compared to the normal brain tissues (all P<0.05)." (PMID 25872784, 2015). "ATF3 was also highly expressed in the glioblastoma cell line, U373MG, suggesting that a high expression level of ATF3 is closely related to the evolution of glioma and its malignant progression." (PMID 25872784, 2015). "Consequently, suppressing ATF3 impeded glioma cell proliferation and migration, counteracting the oncogenic effects induced by CCDC86 overexpression." (PMID 40837407, 2025). "ATF3, a common stress sensor, is involved in iron death induction in a variety of diseases, with therapeutic effects on the progression of gastric cancer, glioma, rectal cancer, and other diseases." (PMID 39801194, 2025). "The interaction between CCDC86 and BHLHE40 appears to be crucial for the transcriptional activation of ATF3, which may contribute to the oncogenic properties of glioma cells." (PMID 40837407, 2025). "Another study showed that Atf3 could promote glioma cell ferroptosis by increasing iron and H2O2 content." (PMID 38802919, 2024). "Furthermore, a study revealed that upon endoplasmic reticulum (ER) stress induced by brucine, activating transcription factor 3 (ATF3) was upregulated and translocated to the nucleus of glioma cells." (PMID 35805884, 2022). "Moreover, Western blotting revealed that GRP78, ATF4, and ATF3 were all time-dependently upregulated in the glioma cells treated with 500 μM H2O2 alone." (PMID 34112960, 2021). "Thus, ATF3 contributed to brucine-induced glioma cell death by reinforcing iron-dependent lipid peroxidation." (PMID 34112960, 2021). "Similarly, we found in this study that GRP78, PERK, and ATF4, as well as ATF3, were all significantly upregulated in the human glioma cells stressed with H2O2 alone." (PMID 34112960, 2021). "ATF3 expression negatively correlated with maspin expression, and the relative protein and mRNA expression of maspin was reduced with the increasing pathological grade of the glioma." (PMID 25872784, 2015). "Taken together, these results suggest that ATF3 promotes the progression of human gliomas." (PMID 25872784, 2015). "Notably, Activating Transcription Factor 3 (ATF3) enhances glioma cell ferroptosis by promoting hydrogen peroxide and iron accumulation, whereas Activating Transcription Factor 4 (ATF4) triggers ferroptosis through Solute Carrier Family 7 Member 11 (SCL7A11)/SCX-dependent mechanism." (PMID 39857625, 2024). "However, it remains elusive whether ATF3 plays a role in regulation of glioma cell ferroptosis via promotion of intracellular H2O2 accumulation." (PMID 34112960, 2021). "In our investigation, we found that elevated CCDC86 expression promoted glycolysis by up-regulating ATF3 and activating the ERK/MAPK pathway, thus driving glioma tumorigenesis." (PMID 40837407, 2025).
glioma (continued). "Further analysis of ATF3 expression in glioma and normal tissue samples from the GEO database (GSE16011) indicated higher expression in glioma (Padj = 0.00578)." (PMID 40837407, 2025). "In glioma, HOXA-AS2 affects the expression of E2F8, E2F1, ATF3, and STAT1, promoting the proliferation of glioma stem cells (GSCs) and enhancing their aggressiveness." (PMID 38311789, 2024). "The potential antitumor effects of cannabinoids through the Notch1 signaling pathway were previously demonstrated in glioma, where THC induced the expression of p8 protein, upstream to ATF3/4." (PMID 39258755, 2024). "Currently, several studies have demonstrated that ATF3 overexpression contributes to the increases in H2O2 and iron, which mediate ferroptosis in retinal pigment epithelial cells and glioma cells." (PMID 37874483, 2024). "More importantly, NPCs migrate into high-grade astrocytomas to reduce glioma expansion and prolong survival by release of fatty acid ethanolamides by triggering a TRPV1-dependent astrocytoma death, via the activation of ATF3 of the ER stress pathway." (PMID 34440820, 2021). "The protein expression of ATF3 and MMP2 in the glioma tissues was evidently higher than that in the normal brain tissues (P>0.05)." (PMID 25872784, 2015). "Spearman’s rank correlation analysis revealed that the protein expression of ATF3 and MMP2 positively correlated with the pathological grade of the glioma (ρ=0.735, P<0.01; ρ =0.446, P<0.01, respectively)." (PMID 25872784, 2015). "Collectively, ATF3-regulated SDHA expression could be repressed by EPIC, resulting in mitochondrial respiration disruption and altered metabolic responses in glioma cells." (PMID 36276638, 2022). "Moreover, knockdown of ATF3 prevented brucine-induced accumulation of iron and H2O2 and glioma cell death." (PMID 34112960, 2021). "The potential molecular mechanism of Withaferin A in glioma may be exerted by NF-KB nuclear translocation, activation of caspase cascade and activating transcription factor 4(ATF4)-ATF3-CHOP axis." (PMID 34164339, 2021). "The objective was to elucidate the role of ATF3, maspin and MMP2 in the development of gliomas." (PMID 25872784, 2015). "In this study, we found that the ATF3 protein and mRNA levels in the human glioma tissues positively correlated with the expression of MMP2, and their expression was increased with the increasing pathological grade of the glioma." (PMID 25872784, 2015). "Immunohistochemical staining, western blot analysis and RT-qPCR revealed that the mRNA and protein levels of ATF3 and matrix metalloproteinase 2 (MMP2) were higher in the glioma than in the normal human brain tissues, and that their levels were proportional to the pathological grades." (PMID 25872784, 2015). "Furthermore, ATF3 emerged as a downstream target gene of CCDC86, as its knockdown could counteract the oncogenic effects induced by CCDC86 overexpression in glioma cells." (PMID 40837407, 2025).